HDAC4 (histone deacetylase 4)
Diseases named in the same sentence as HDAC4 in open-access papers (continued):
Sharing a sentence is not in itself a finding about the gene and the disease.
Ataxia (1 paper, 2021). Ataxia refers to impaired coordination of voluntary muscle movement. "Based on the findings reported here, it is possible that dysregulation of ZASC1:ZBTB2:HDAC4 interactions contributes to these ataxias." (PMID 33635925, 2021). "Further, both HDAC4 and ZASC1 have been linked to inherited ataxias." (PMID 33635925, 2021).
autoimmune disease (1 paper, 2022). A disorder resulting from loss of function or tissue destruction of an organ or multiple organs, arising from humoral or cellular immune responses of the individual to their own tissue constituents. "However, apart from the experimental findings, few studies have explored the clinical implication of HDAC4 in autoimmune diseases such as AS, let alone its relevance to treatment response in AS." (PMID 35602496, 2022). "Third, the relationship between HDAC4 and the disease progression and treatment response in other autoimmune diseases could be further explored." (PMID 35602496, 2022). "Histone deacetylase 4 (HDAC4) regulates the progression of autoimmune diseases." (PMID 35602496, 2022).
bladder transitional cell carcinoma (1 paper, 2011). The most common morphologic subtype of urinary bladder carcinoma (over 90% of cases). "The results of our IHC studies further indicated a strong correlation between the over-expression of the HDAC4 and the occurrence of urinary bladder transitional cell carcinomas." (PMID 21507255, 2011). "Given the similarity between the HDAC2 and HDAC4 proteins in both their functions, these results suggest that only certain HDACs are involved in the XPC gene silencing in the urinary bladder transitional cell carcinomas." (PMID 21507255, 2011).
bladder tumors (1 paper, 2011). "The results of our IHC study indicated that the frequency of the HDAC4-positive tissue specimens was much higher in the bladder tumors than in the normal bladder tissues." (PMID 21507255, 2011). "Determination of the presence of the HDAC4 in both normal and cancerous bladder tissues from bladder tumor tissue arrays." (PMID 21507255, 2011). "The results of our IHC studies revealed strong correlation between over-expression of the HDAC4 and the occurrence of bladder tumors." (PMID 21507255, 2011).
bullous pemphigoid (1 paper, 2023). Bullous pemphigoid (BP) is the most common form of autoimmune bullous dermatosis. "HDAC4 is also associated with B-cell lymphoma 6 (BCL6), a repressor protein essential for germinal center B cells and T follicular helper cells (Tfh), known to be increased in the blood of bullous pemphigoid patients." (PMID 38255677, 2023).
chordoma (1 paper, 2010). Chordomas are rare malignant tumors arising from embryonic remnants of the notochord in axial skeleton. "Transfection of chordoma cell lines with miR-1 resulted in suppression of known miR-1 targets, such as Met and HDAC4, which are found to be overexpressed in chordoma." (PMID 24281118, 2010).
chronic obstructive pulmonary disease (1 paper, 2021). A chronic and progressive lung disorder characterized by the loss of elasticity of the bronchial tree and the air sacs, destruction of the air sacs wall, thickening of the bronchial wall, and mucous accumulation in the bronchial tree. "Similarly, upregulated HDAC4 expression has been found in the main respiratory muscle of patients with chronic obstructive pulmonary disease." (PMID 34118928, 2021).
cleft palate (1 paper, 2012). Cleft palate is a fissure type embryopathy that affects the soft and hard palate to varying degrees. "Since defects in HDAC4 in humans are associated with cleft palate, understanding the function of this gene in the normal specification and migration of CNC cells may reveal how loss of HDAC4 causes craniofacial malformations." (PMID 22676467, 2012).
colitis (1 paper, 2023). Inflammation of the colon. "From these factors, RNA expression of Bax, Hdac4, IL-18, Casp8 and Hif1 returned to baseline level compared to the colitis- associated upregulation, when MMs were depleted with l-clodronate during DSS-treatment." (PMID 38105266, 2023). "The expression of Hdac4, IL-18 and Casp8 showed a trend similar to Bax’s, where colitis-associated overexpression was diminished in the case of concurrent l-clodronate administration." (PMID 38105266, 2023). "Moreover, DSS-treated mice administered concurrently with l-clodronate show milder clinical symptoms of colitis, intestinal transit times similar to control animals, and decreased expression of factors implicated in neural inflammation and death, including Bax, Hdac4, IL-18, Casp8 and Hif1a." (PMID 38105266, 2023).
endothelial dysfunction (1 paper, 2025). In vascular diseases, endothelial dysfunction is a systemic pathological state of the endothelium (the inner lining of blood vessels) and can be broadly defined as an imbalance between vasodilating and vasoconstricting substances produced by (or acting on) the endothelium. "Together, these findings identify sodium acetate as a potent senomorphic agent that mitigates PAA-induced endothelial dysfunction through a mechanism distinct from PAA’s mechanism in HDAC4-regulated SASP activation." (PMID 40355758, 2025).
familial dilated cardiomyopathy (1 paper, 2021). A a genetic form of heart disease that occurs when heart (cardiac) muscle becomes thin and weakened in at least one chamber of the heart, causing the open area of the chamber to become enlarged (dilated). "It has been identified that DKK3 downregulates key proteins in non-canonical Wnt pathway such as c-Jun N-terminal kinase (JNK), Ca2+/calmodulin-dependent protein kinase II (CAMKII), and histone deacetylase 4 (HDAC4) in familial dilated cardiomyopathy." (PMID 33670899, 2021).
fibromyalgia (1 paper, 2023). A chronic disorder of unknown etiology characterized by pain, stiffness, and tenderness in the muscles of neck, shoulders, back, hips, arms, and legs. "HDAC4 has previously been implicated in chronic pain disorders such as fibromyalgia." (PMID 38087366, 2023).
folate deficiency (1 paper, 2016). A nutritional condition produced by a deficiency of FOLIC ACID in the diet. "FD-conditioned HCC cells contained a lower level of miR-22 leading to the elevated level of HDAC4, an established oncogenic epigenetic modifier, may provide a partial and mechanistic explanation for the association between cancer development and folate deficiency." (PMID 27119349, 2016).
gingivitis (1 paper, 2025). A disorder involving inflammation of the gums; may affect surrounding and supporting structures of the teeth. "Additionally, a clinical study analyzing saliva samples reported downregulation of the histone deacetylase genes HDAC4, HDAC8, and HDAC10 in gingivitis, and HDAC4, HDAC6, HDAC8, and HDAC9 in periodontitis." (PMID 41228440, 2025).
glaucoma (1 paper, 2023). Increased pressure in the eyeball due to obstruction of the outflow of aqueous humor. "Little is known of what the function of HDAC4 in glaucoma is, but emerging evidence has shown HDAC4 has its importance in regulating neurogenesis." (PMID 37605653, 2023). "This study identified IL18, TLR9, NFKB1, HDAC4, FKBP2, and KITLG as hub genes in glaucoma that are gut microbiota-related as well as showed that the regulation of immune response by gut microbiota is associated with glaucoma." (PMID 37605653, 2023). "NFKB1, TLR9, and HDAC4 were predicted to be upregulated in glaucoma and their mRNA level increased according to the RT-qPCR data, meanwhile, IL18 was predicted to be downregulated in glaucoma and its mRNA level was also increased according to RT-qPCR." (PMID 37605653, 2023).
glomerulopathy (1 paper, 2016). "Histone deacetylase 4 inhibition could ameliorates podocyte injury and attenuates glomerulopathy in DN, and the maintenance of autophagy in podocytes was suggested to be the mechanism underlying." (PMID 27077005, 2016).
hepatitis C virus infection (1 paper, 2023). A viral infection caused by the hepatitis C virus. "In hepatitis C virus infection, the viral core protein increased STAT1 acetylation and blocked its phosphorylation by decreasing the transcription level of HDAC4, resulting in reduced host immune responses to IFN-α stimulation." (PMID 37052505, 2023).
infarction (1 paper, 2021). A localised pathological necrosis of tissue resulting from obstruction of the blood supply usually by a thrombus, an embolus, or vascular torsion. "Adding to this knowledge of HDACs, our study demonstrated that HDAC4 silencing facilitates the improvement of IRI-induced infarction and the resultant myocardial injury both in vivo and in vitro." (PMID 34526481, 2021).
Infertility (1 paper, 2023). "Four transcription regulators (CCND1, FOXO1, CREB1, and HDAC4) were found to be targeted by DE-miRNAs, suggesting that they could be critical regulators in events associated with EMS and may play a role in infertility." (PMID 38002087, 2023).
kidney cancer (1 paper, 2015). Primary or metastatic malignant neoplasm involving the kidney. "Inhibition of HDAC4 in kidney cancer cells by specific short hairpin RNA resulted in increased acetylation and degradation, as well as reduced transcriptional activity of HIF-1α, as a result of HDAC4 reduction and subsequent acetylation of N-terminal lysines." (PMID 25608569, 2015).
kidney injury (1 paper, 2025). Trauma to the kidney. "Collectively, these findings suggest that HDAC4 regulates Foxo3a subcellular localization by promoting its phosphorylation, thereby restricting its nuclear activity and downstream target gene regulation during IR-induced kidney injury." (PMID 41282137, 2025).
Knee Osteoarthritis (1 paper, 2025). "This study demonstrates that HBP‐A alleviates knee osteoarthritis progression by simultaneously preserving articular cartilage integrity and mitigating quadriceps atrophy through inhibition of the MLK3/P38 MAPK/HDAC4 axis." (PMID 40318007, 2025).
left ventricular hypertrophy (1 paper, 2018). Enlargement of the LEFT VENTRICLE of the heart. "Likewise, transgenic mice with mutant HDAC4 displayed greater left ventricular hypertrophy and a larger cross-sectional area of LV myocytes." (PMID 30134825, 2018).
lung injury (1 paper, 2018). "In addition, HDAC4 inhibition has been shown to prevent increases in MMP-9 and hence EMT in a mouse model of bleomycin-induced acute lung injury." (PMID 30068332, 2018). "In addition, inhibiting HDAC4 suppressed MMP-9 elevation and hence EMT in a mouse model of bleomycin-induced acute lung injury." (PMID 30068332, 2018).
metastatic disease (1 paper, 2024). "Similarly, HDAC-4 immunopositivity was correlated with the absence of metastatic disease at diagnosis in serous carcinomas." (PMID 38790909, 2024).
migraine (1 paper, 2023). "HDAC4 is highly expressed in the brain, plays a major role in synaptic plasticity, and modulates the expression and release of several neuroinflammation markers which have been implicated in migraine pathophysiology." (PMID 38087366, 2023). "Therefore, a pathway involving HDAC4 and estrogen might also partially explain why women have a higher risk for migraine chronification." (PMID 38087366, 2023). "HDAC4 encodes a Class IIa histone deacetylase, and along with co-repressors such as MEF2D encoded by a previously reported migraine GWAS locus, its activity targets lysine residues on core histone tails to repress transcription." (PMID 38087366, 2023). "HDAC4 is highly expressed in the brain and is a major player in synaptic plasticity and modulates the expression and release of several neuroinflammation markers, including HMGB1 and NF-κB, which have been implicated in migraine pathophysiology." (PMID 38087366, 2023).
myelodysplastic syndrome (1 paper, 2021). A clonal hematopoietic disorder characterized by dysplasia and ineffective hematopoiesis in one or more of the hematopoietic cell lines. "In myelodysplastic syndrome (MDS) and AML cells, HDAC4 inhibition leads to the downregulation of TET2 and the subsequent decrease in the abundance of 5hmeC marks." (PMID 33805247, 2021).
myeloid neoplasm (1 paper, 2020). Proliferation of myeloid cells originating from a primitive stem cell. "To further characterize HDAC4 function in myeloid neoplasms, we analyzed HDAC4 expression levels in AML patients with normal karyotype versus healthy donors (GSE13159)." (PMID 32726753, 2020).
non-alcoholic steatohepatitis (1 paper, 2023). "Furthermore, we showed that loss of Hdac4 in macrophages exacerbated inflammation of liver and adipose tissue in male mice with diet-induced non-alcoholic steatohepatitis." (PMID 37049466, 2023).
psychosomatic disorders (1 paper, 2025). "This review first outlines how epigenetic dysregulation contributes to psychosomatic disorders through altered expression of genes such as GRM2, TRPA1, SLC6A4, NR3C1, leptin, BDNF, NAT15, HDAC4, PRKCA, RTN1, PRKG1, and HDAC7." (PMID 41439979, 2025).
renal carcinoma (1 paper, 2015). A carcinoma arising from the epithelium of the renal parenchyma or the renal pelvis. "HDAC4 interacts with hypoxia-inducible factor 1α (HIF-1a) and mediate angiogenesis in renal carcinoma cells." (PMID 25504437, 2015).
serous carcinomas (1 paper, 2024). "HDAC-4 positivity was marginally associated with favorable prognosis in serous carcinomas in univariate survival analysis (p = 0.086), but this correlation was not significant in multivariate analysis." (PMID 38790909, 2024). "In the univariate survival analysis for overall survival, only HDAC-4 immunopositivity in serous carcinomas seemed to be associated with a better OS, which was a correlation of marginal significance only (log-rank test, p = 0.086)." (PMID 38790909, 2024). "Another interesting finding of the present investigation is that the presence of HDAC-4 expression in serous carcinomas connotes a better survival probability." (PMID 38790909, 2024). "HDAC-4 positivity was associated with lower FIGO-stage (p = 0.045) and T-category (p = 0.043) and the absence of lymph node (p = 0.05) or distant metastasis (p = 0.09) in serous carcinomas." (PMID 38790909, 2024).
skin cancer (1 paper, 2023). "The study further suggested that SFN and iberin reduced the viability of skin cancer cells (A375, Hs294T, and B16F10) and decreased the expression of HDACs (HDAC1, HDAC2, HDAC4, and HDAC6)." (PMID 36765652, 2023). "The mechanistic insights revealed a decreased methylation ratio of CpG dinucleotides in the promoter region of Nrf2 in SFN-treated skin cancer cells, and SFN also attenuated the expression of HDACs (HDAC1, HDAC2, HDAC3, and HDAC4) and DNMTs (DNMT1, DNMT3a, and DNMT3b)." (PMID 36765652, 2023).
spinocerebellar ataxia type 1 (1 paper, 2015). Spinocerebellar ataxia type 1 (SCA1) is a subtype of type I autosomal dominant cerebellar ataxia (ADCA type I) characterized by dysarthria, writing difficulties, limb ataxia, and commonly nystagmus and saccadic abnormalities. "A causative role for HDAC4 has been also described in SCA-1 (Spinocerebellar Ataxia Type 1) as a modulator of Ataxin-1." (PMID 25759639, 2015).
testicular tumor (1 paper, 2014). "Altogether, we propose that the testicular tumor in our case might be a phenotypic consequence of the haploinsufficiency of HDAC4 and the duplication of DVL1." (PMID 24755370, 2014). "Therefore, it is unlikely that haploinsufficiency of HDAC4 contributed per se to the testicular tumor formation in this case, whereas there is little evidence that other genes within the deleted region are associated with carcinogenesis." (PMID 24755370, 2014).
thymic carcinoma (1 paper, 2023). Thymic carcinoma (TC) is a type of thymic epithelial neoplasm characterized by a high malignant potential. "B2- and B3-type TETs and thymic carcinomas were more frequently positive for HDAC4 compared to the other WHO types (Fisher’s exact test, p = 0.03, 63% vs. 37%)." (PMID 36901692, 2023). "Moreover, epithelial rich (namely B3 and thymic carcinoma) TETs tended to show a higher HDAC4 H-score compared to the rest of the types (Mann–Whitney, p = 0.061, median value 60 vs. 25), but this relationship was of marginal significance." (PMID 36901692, 2023).
thymic epithelial tumors (1 paper, 2023). "In this study we attempt the first comprehensive evaluation of six class I (HDAC1, HDAC2, HDAC3) and II HDACs (HDAC4, HDAC5, HDAC6) expression patterns in thymic epithelial tumors (TETs), with the aim of identifying their possible association with a number of clinicopathological parameters." (PMID 36901692, 2023).
α-synucleinopathies (1 paper, 2023). "This provides corroborating evidence for the neuroprotective role of HDAC4 modulation in α-synucleinopathies." (PMID 37190635, 2023).